DDX59 (DEAD-box helicase 59)
Synonyms: ZNHIT5; DKFZP564B1023; OFD5
Tractability: PROTAC: UniProt records ubiquitination sites on it; ubiquitination databases record sites on it; its protein half-life has been measured.
Target class: Enzyme; Hydrolase
Gene: Protein-coding gene on chromosome 1 (200,623,896 to 200,670,049, reverse strand). Ensembl gene ENSG00000118197.
Subcellular location: Cytoplasm; Nucleus
Subcellular location (Human Protein Atlas): Actin filaments; Nucleoplasm; Basal body; Centrosome; Primary cilium; Primary cilium tip; Vesicles
Gene Ontology:
Molecular function: ATP binding; ATP hydrolysis activity; nucleic acid binding; RNA helicase activity
Cellular component: nucleoplasm; cytoplasm; nucleus
Genetic constraint (gnomAD): Loss-of-function variants: 36 observed, 55.06 expected, observed/expected ratio (o/e) 0.65, 90% interval 0.5 to 0.86. The upper end of that interval is the gene's LOEUF score, 0.86, which puts it in group 3 of 6, group 1 being the genes least tolerant of losing a copy. Missense variants: 649 observed, 740.78 expected, observed/expected ratio (o/e) 0.88, 90% interval 0.82 to 0.94. Synonymous variants: 250 observed, 256.56 expected, observed/expected ratio (o/e) 0.97, 90% interval 0.88 to 1.08.
Gene-disease validity (ClinGen):
ClinGen rates the evidence that DDX59 causes each of these diseases.
ciliopathy (autosomal recessive): Limited. A genetic disorder of the cellular cilia or the cilia anchoring structures, the basal bodies, or of ciliary function.
Homologues: Orthologues: chimpanzee DDX59 (99% identical), macaque DDX59 (97% identical), dog DDX59 (89% identical), guinea pig DDX59 (84% identical), mouse Ddx59 (84% identical), rat Ddx59 (84% identical), pig DDX59 (79% identical), rabbit DDX59 (78% identical), tropical clawed frog ddx59 (60% identical), zebrafish ddx59 (58% identical). Paralogues in human: DDX23 (31% identical), DDX46 (27% identical), DDX42 (27% identical), DDX3Y (26% identical), DDX41 (26% identical), DDX3X (26% identical), DDX4 (25% identical), DDX5 (25% identical), DDX17 (25% identical), DDX43 (25% identical), DDX53 (24% identical), DDX27 (24% identical), and 26 more.
Diseases named in the same sentence as DDX59 in open-access papers:
DDX59 is named in the same sentence as 21 diseases in open-access papers, as found by Europe PMC text mining. Sharing a sentence is not in itself a finding about the gene and the disease. The quoted sentences say what the papers report.
lung adenocarcinoma (3 papers, 2017 to 2022). A carcinoma that arises from the lung and is characterized by the presence of malignant glandular epithelial cells. "Reportedly, DDX59 is highly expressed in lung adenocarcinoma tissues and contributes to the growth of EGFR− lung cancer cells." (PMID 35113786, 2022). "DDX59 (aGRP = 0.645) has been extensively observed to be highly expressed in lung adenocarcinoma and promote DNA replication in lung cancer development." (PMID 30390627, 2018). "Among all the subtypes of NSCLCs, positive staining for DDX59 was observed in most lung adenocarcinoma." (PMID 28090355, 2017). "We searched the TCGA database and found that DDX59 is amplified in ~9% of human lung adenocarcinoma cancers." (PMID 28090355, 2017). "We report that DDX59 protein is overexpressed in a significant number of human non-small cell cancers, especially in lung adenocarcinoma (up to 56%)." (PMID 28090355, 2017). "To check whether DDX59 protein is indeed elevated in lung adenocarcinoma, we further performed IHC for 33 additional cases of human lung adenocarcinoma tissues with paired tumor adjacent normal and normal tissues." (PMID 28090355, 2017). "In lung adenocarcinoma, DDX59 protein expression does correlate with tumor stages." (PMID 28090355, 2017). "In this report, we found DDX59 overexpressed in lung adenocarcinoma." (PMID 28090355, 2017). "We found that DDX59 is highly expressed in lung adenocarcinoma tissues." (PMID 28090355, 2017).
lung carcinoma (3 papers, 2017 to 2022). "We then expressed this protein in lung cancer cells and found DDX59 predominantly expressed in the nucleus." (PMID 28090355, 2017). "Our study reveals for the first time that DDX59 has an important role in lung cancer development through promoting DNA replication." (PMID 28090355, 2017). "Three lung cancer cell lines, including H1299, H23, and SK-LU-1, contain higher levels of DDX59 mRNA as compared with normal lung cell lines by up to twofold." (PMID 28090355, 2017). "To check DDX59 protein levels in cancer cell lines, we analyzed several different lung cancer cell lines and the immortalized human lung epithelial cell line, BeaS2B, as well as normal lung cell line, WI-38, primary human fibroblast, HFF." (PMID 28090355, 2017). "To investigate whether DDX59 protein is highly expressed in lung cancers, we first performed an immunohistochemistry (IHC) staining to detect DDX59 in a human NSCLC tissue array containing 95 cases of NSCLCs." (PMID 28090355, 2017). "We found DDX59 highly expressed in many lung cancer cell lines as compared with normal lung cells." (PMID 28090355, 2017). "From these IHC results, it is clear that DDX59 localized mostly in the nucleus rather than in the cytosol of lung cancer tissues." (PMID 28090355, 2017).
glioma (2 papers, 2015 to 2022). A benign or malignant brain and spinal cord tumor that arises from glial cells (astrocytes, oligodendrocytes, ependymal cells). "Reportedly, miR-628-5p impedes the proliferation of glioma cells by negatively regulating DDX59 expression." (PMID 35113786, 2022). "These experiments indicated that DLGAP1-AS1 could promote the proliferation, migration, invasion, and EMT of glioma cells by sponging miR-628-5p and upregulating DDX59 expression." (PMID 35113786, 2022). "The DLGAP1-AS1/miR-628-5p/DDX59 axis regulates glioma progression." (PMID 35113786, 2022).
breast carcinoma (1 paper, 2017). "DDX59 gene is also amplified in several other cancer types including breast cancer, liver cancer, and melanoma." (PMID 28090355, 2017).
developmental delay (1 paper, 2022). "As a member of the DDX5.Dbp2 subfamily, DDX59 has nine highly conserved sequences, the most characteristic regions including aspartate-glutamate-alanine-aspartate (D-E-A-D), which has been reported to be involved in malignancies, neurological development, and developmental delay." (PMID 36081993, 2022).
Intellectual disability (1 paper, 2024). "Moreover, it is striking that mutations in other DEAD box RNA helicases, such as DHX30, DDX3X, or DDX59, all cause intellectual disability or other neurodevelopmental disorders." (PMID 38536035, 2024).
leukoencephalopathies (1 paper, 2018). "We showed a reduction of mutant cDNA and perturbation of SHH signaling from patient‐derived cell lines; furthermore, analysis of human brain gene expression provides evidence that DDX59 is enriched in oligodendrocytes and might act within pathways of leukoencephalopathies‐associated genes." (PMID 29127725, 2018).
preeclampsia (1 paper, 2020). Preeclampsia is a hypertensive disorder of pregnancy that is characterized by new-onset hypertension with proteinuria presenting after 20 weeks of gestation, and depending on mild or severe forms may initially present with severe headache, visual disturbances, and hyperreflexia. "A recent study has shown that DDX59 is upregulated in syncytiotrophoblasts in severe preeclampsia patients compared to controls." (PMID 33308293, 2020).
tumor (2 papers, 2017 to 2022). "DDX59 knockdown reduced cell proliferation, anchorage-independent cell growth, and caused reduction of tumor formation in immunocompromised mice." (PMID 28090355, 2017). "We found that approximately half of these tumor tissues showed positive staining for DDX59, whereas in three normal lung tissues, DDX59 was weakly expressed." (PMID 28090355, 2017). "We found that DDX59 positively expressed in 56% of all cases in the tumor tissues, whereas most paired tumor adjacent and normal tissues show negative staining for DDX59." (PMID 28090355, 2017).
cancer (1 paper, 2017). A tumor composed of atypical neoplastic, often pleomorphic cells that invade other tissues. "So far, this is the first report about DDX59 in human cancers and about its function in cell proliferation." (PMID 28090355, 2017). "DDX59 deregulation might contribute to the development of a wide variety of cancers." (PMID 28090355, 2017). "Our report on DDX59 function underscores the potential importance and diversity of DEAD/DEAH helicases in promoting cancer and warrants a broader evaluation of the activities of this protein family." (PMID 28090355, 2017).
neurological diseases (1 paper, 2018). "DDX59 encodes a DEAD‐box RNA helicase and its role in brain function and neurological diseases is unclear." (PMID 29127725, 2018).
DDX59 also shares sentences with these, for which no sentence is quoted: cardiovascular disease (1 paper); epilepsy (1); liver cancer (1); melanoma (1); neurodevelopmental disorder (1); Nicolaides-Baraitser syndrome (1); Obesity (1); orofaciodigital syndrome (1); orofaciodigital syndrome V (1); type 2 diabetes (1).